CXCR4 (C-X-C motif chemokine receptor 4)
Diseases named in the same sentence as CXCR4 in open-access papers (continued):
Sharing a sentence is not in itself a finding about the gene and the disease.
Sepsis (continued). "In a model of polymicrobial sepsis, blocking CXCR4 decreased sepsis-induced mortality." (PMID 32210974, 2020). "Nevertheless, data on CXCR4 and sepsis is still conflicting." (PMID 32210974, 2020). "Our data suggest that SDF-1α and CXCR-4 signaling could play a crucial role in EPC homing in the course of sepsis." (PMID 29796010, 2018). "Given the finding that CXCR4 is upregulated on CD4+ and CD8+ T cells during sepsis, we hypothesized that blocking these signals using a CXCR4 blocking agent could improve survival and immune dysregulation in a murine model of polymicrobial sepsis." (PMID 29232699, 2017). "Taken together, these results characterize CXCR4 as an important pathway that modulates immune dysfunction and mortality following sepsis, which may hold promise as a target for future therapeutic intervention in septic patients." (PMID 29232699, 2017). "Moreover, the effect of sepsis on CXCR4 expression was T cell subset-specific, in that expression was not upregulated on CD8+ TCM, or on TEM in either the CD4+ or CD8+ compartments." (PMID 29232699, 2017). "However, this may create a feedback loop, as the upregulated production of IFN-gamma or a higher bacterial load (LPS) can increase the frequency of CXCR4+ PD-L1+ neutrophils, further amplifying the hyperinflammatory state in sepsis." (PMID 40241761, 2025). "Thus, our study provides first indications, that the SDF-1α/CXCR-4 signalling axis might be involved in EPC homing to damaged endothelial layers in sepsis, which is the prerequisite step for further EPC based regeneration processes." (PMID 29796010, 2018). "Thus, it is possible that increased CXCR4 expression during sepsis may amplify this pathway and result in enhanced IL-2, IL-4, and/or IL-10 secretion." (PMID 29232699, 2017). "Next, to determine the effect of CXCR4 antagonism on the systemic cytokine environment during sepsis, we studied the levels of multiple circulating pro-inflammatory and anti-inflammatory cytokines known to be elevated in sepsis in sham controls, CLP animals, and CLP animals treated with plerixafor." (PMID 29232699, 2017). "Moreover, in the CLP sepsis model, expression of CXCR4 on HSPCs was increased." (PMID 26272069, 2015). "Conversely, in the sepsis group, the probability of cellular communication between NKT and CD16Mono via MIF - (CD74+CXCR4) exhibited the highest magnitude." (PMID 40375981, 2025). "Conversely the upregulated genes in sepsis Th1 cells showed enhanced endopeptidase activity (GAPDH; 0.75log2FC) and angiogenesis related (XBP1, CXCR4, and BTG1; 0.93, 0.66, and 0.64log2FC, respectively) pathways." (PMID 41208955, 2025). "The limitations of this study include the incomplete exploration of the effector mechanisms by which CXCR4+ PD-L1+ neutrophils and monocytes contribute to the worsening of CLP-sepsis." (PMID 40241761, 2025). "In sepsis, Microglia 1 exhibited strong upregulation of pro-inflammatory genes (e.g., GPNMB, CXCR4, HLA-DRB5) and downregulation of BBB-supportive genes (e.g., SPARCL1, MAP1B), indicating a highly reactive phenotype." (PMID 41030458, 2025). "Decreased CXCR4 expression, in turn, decreases retention of ILC2p in BM, and increases recruitment of ILC2 in the lung during sepsis." (PMID 35272622, 2022). "Hence, our data suggest that manipulation of SP1 or CXCR4 may be an effective approach to promote the prevention or recovery of septic myocardial injury, and thereby, serve as a potential therapeutic strategy for sepsis." (PMID 35048778, 2022). "Hence, our findings provide evidence that manipulation of SP1 or CXCR4 may be an effective approach to promote prevention or recovery of septic myocardial injury, and thereby, may serve as a potential therapeutic strategy for sepsis." (PMID 35048778, 2022). "We evaluated the effects of selective CXCR4 and CXCR7 inhibition on PNCs and NETs in zymosan- and fecal-induced sepsis." (PMID 34948374, 2021).
Sepsis (continued). "Next, we sought to verify the protective properties of specific CXCR4 and CXCR7 inhibition in a polymicrobial model of peritonitis and peritonitis-related sepsis." (PMID 34948374, 2021). "The presented study provides new insight on the mechanism of a selective inhibition of CXCR4 (AMD3100) and CXCR7 (CCX771) in two models of peritonitis and peritonitis-related sepsis by injection of zymosan and fecal solution." (PMID 32210974, 2020). "Other than these, it was verified that in sepsis-induced ALI, reduced CXCR4+ aged neutrophils by targeting junctional adhesion molecule-C attenuates lung injury and systemic inflammation." (PMID 32522221, 2020). "The application of CTCE-0214, a SDF-1α peptide analog and CXCR-4 agonist, significantly suppressed TNF and interleukin (IL)-10 concentrations and improved survival in murine systemic inflammation and sepsis." (PMID 29796010, 2018). "In this series of investigations, we found that CXCR4 blockade improved survival in murine polymicrobial sepsis, increased the absolute number of circulating CD4+ and CD8+ T cells, and mitigated sepsis-induced T cell exhaustion phenotypes." (PMID 29232699, 2017). "We probed the mechanistic basis for these findings and found that CXCR4 antagonism significantly increased the number of peripheral CD4+ and CD8+ T cells following sepsis." (PMID 29232699, 2017). "Our study shows that CXCR4 is upregulated on naïve CD4+ and CD8+ T cells, as well as CD4+ TCM, during sepsis." (PMID 29232699, 2017). "Recently, the diagnostic value has been shown in neonatal sepsis, where elevated CXCR4 and CXCL12 levels were accompanied by increased sepsis severity." (PMID 26375818, 2015). "The CXCR4+ PD-L1+ neutrophils population and elevated plasmatic IFN-gamma levels highlighted here present potential targets for therapeutic modulation in the clinical sepsis hyperinflammatory phenotype." (PMID 40241761, 2025). "Ultimately, by taking the intersection of the results from the three machine learning methods, we identified six feature genes in sepsis: CD81, CLU, GLRX, CKAP4, DPEP2, and BCL11B; and seven feature genes in atrial fibrillation: LDHB, CD81, PFKFB2, CKAP4, CXCR4, DPEP2, and RORA." (PMID 41359645, 2025). "Notably, the MIF–(CD74+CXCR4), HLA–KIR, ANXA1–FPR2, and CD99–CD99 signaling pathways were significantly upregulated in sepsis." (PMID 41346577, 2025). "Under high λ conditions, we observed that the genes GLPX, CKAP4, CXCR4, and CLU maintained significant positive values, suggesting that these four genes may be key predictors of sepsis." (PMID 41359645, 2025). "Our observation that P529 partially rescued mortality in the TRALI model and prolonged survival in LPS-induced sepsis model suggests that inhibitors of PTP1B function, at least in part, through suppressing AKT/mTOR-mediated CXCR4 signaling, to promote neutrophil aging." (PMID 35866483, 2022). "Targeting Cxcr4 using a pepducin agonist protected mice from tissue damage during sepsis without affecting the bacterial load, indicating a Cxcr4-dependent disease tolerance mechanism." (PMID 36178806, 2022). "Consequently, we investigated the effects of CXCR4 and CXCR7 inhibition on PNC formation during sterile and polymicrobial sepsis." (PMID 34948374, 2021). "In the presented study, we investigated the specific role of the SDF-1 receptors CXCR4 and CXCR7 during acute inflammatory peritonitis and peritonitis-related sepsis concerning the two hallmarks of acute inflammation, migration of PMNs and barrier permeability." (PMID 32210974, 2020). "Since the SDF-1α/CXCR-4-signalling axis impacts EPC recruitment to peripheral tissues, according to our results it could also be involved in promoting EPC homing in sepsis and thereby promote endothelial layer regeneration." (PMID 29796010, 2018). "Moreover, mice treated with the CXCR4 antagonist contained fewer PD-1+ LAG-3+ 2B4+ cells, suggesting that blockade of CXCR4 mitigates CD4+ T cell exhaustion during sepsis." (PMID 29232699, 2017).
Sepsis (continued). "Only a few studies have quantified CXCL12 or CXCR4 expression directly in human lung tissues or characterized temporal changes during disease progression, and interventional clinical data targeting this axis in sepsis or ALI are effectively nonexistent." (PMID 41614816, 2025). "Strikingly, activating, but not antagonizing, Cxcr4 during sepsis promoted tissue damage control in our model, which is in conflict with a study showing that Cxcr4 blockade with AMD3100 prior induction of peritonitis prevents neutrophil infiltration and tissue inflammation." (PMID 36178806, 2022). "Thus, CXCR4 and CD69 might contribute to the selective recruitment and retention of CD8+ TN, TCM, and TVM cells in the BM during sepsis, a hypothesis that remains to be evaluated further." (PMID 36148245, 2022). "However, the role of the SDF-1 receptors CXCR4 and CXCR7 in acute inflammatory peritonitis and peritonitis-related sepsis still remained unknown." (PMID 32210974, 2020). "Thus, the upregulation of CXCR-4, c-Kit and RAGE by EPC shown in our study indicates, that these factors could be important mediators of EPC homing in sepsis." (PMID 29796010, 2018). "The finding that blocking the receptor (CXCR4) yields a result distinct from that observed when blocking the ligand (CXCL12) may suggest that one or more alternate binding partners is available and capable of modulating the response during sepsis." (PMID 29232699, 2017). "Taken together with our results, these data suggest that bystander activation of T cells in an inflammatory environment in which CD40 and/or CD134 signals are present in the absence of cognate antigen may drive CXCR4 upregulation during sepsis." (PMID 29232699, 2017). "Thus, identification of the effects of plerixafor on the T cell compartment during sepsis does not preclude the possibility that CXCR4 antagonism could affect other immune cell types during sepsis." (PMID 29232699, 2017). "CXCR-4, c-Kit and RAGE expression in sepsis non-survivors was increased compared to survivors, but these results were not significant." (PMID 29796010, 2018).
acute lymphoblastic leukemia (36 papers, 2009 to 2025). Leukemia with an acute onset, characterized by the presence of lymphoblasts in the bone marrow and the peripheral blood. "In the case of lymphoblastic leukemia tumors (CCRF-CEM)—these cells come from lymphoblastic leukemia and express certain receptors such as CXCR4)." (PMID 39408283, 2024). "High CXCR4 expression is found in B- and T-acute lymphoblastic leukemia (ALL) cells, where it correlates with higher incidence of relapse." (PMID 32260318, 2020). "Sipkins and colleagues have demonstrated that disruption of the interactions between SDF-1 and its receptor CXCR4 inhibits the homing of Nalm-6 cells (an acute lymphoblastic leukaemia cell line) to the BM." (PMID 25015105, 2014). "For instance, in acute lymphoblastic leukemia, high expression of CXCR4 generally correlates with the ability of the leukemic cells to infiltrate extramedullary sites." (PMID 19390584, 2009). "As CXCR7 expression has been reported in some hematologic malignancies, such as acute myeloid or lymphoblastic leukemia, in which CXCR4 has been described as a poor prognostic factor, it would be relevant to study if CXCR7 expression improves the CXCR4 prognostic value." (PMID 29920526, 2018). "For example, in T-cell acute lymphoblastic leukemia (T-ALL), PFKP stimulated T-ALL cell invasion by upregulating the expression of C-X-C chemokine receptor type 4 (CXCR4)." (PMID 37833332, 2023). "A second target for theranostics of AML and Acute Lymphoblastic Leukemia (ALL) is the CXCR4 antigen." (PMID 35865548, 2022). "SDF-1a/CXCR4 axis was also reported to mediated drug resistance in acute lymphoblastic leukemia (ALL)." (PMID 34095111, 2021). "CXCR4-mediated infiltration of the central nervous system is a severe trait of T cell acute lymphoblastic leukemia (T-ALL) and correlates with relapses." (PMID 32903764, 2020). "Although we currently have a good understanding of the role C-X-C chemokine receptor type 4 (CXCR4) plays in T cell acute lymphoblastic leukemia (T-ALL), the mechanism of CXCR4-mediated T-ALL migration remains elusive." (PMID 32903764, 2020). "CXCR4 signaling and its impact on acute lymphoblastic leukemia (ALL) growth in vivo." (PMID 36912771, 2023). "Blocking CXCR4, the receptor for the chemoattractant CXCL12, only partially inhibits acute lymphoblastic leukemia cell invasion of human cerebrospinal fluid." (PMID 37444576, 2023). "At least in acute lymphoblastic leukemia, Rac1 activation is observed in response to the CXCL12/CXCR4 axis." (PMID 36009428, 2022). "Growth arrest‐specific (GAS2) interacts with C‐X‐C motif chemokine receptor 4 (CXCR4) and enhances the stability of CXCR4 in T‐cell acute lymphoblastic leukemia (T‐ALL) cells, and the GAS2/CXCR4 axis activates the expression of NOTCH/c‐MYC and promotes T‐cell leukemogenesis." (PMID 36054080, 2022). "In this study, we have demonstrated that human primary CLL cells generally express high level of CXCR4, and LY2624587 is able to block SDF-1 and CXCR4 mediated cell signaling and induce apoptosis of NHL and lymphoblastic leukemia cells in vitro." (PMID 26954567, 2016). "Consistent with a lack of agonistic function, a CXCR4-expressing murine acute lymphoblastic leukemia (ALL) cell line, which strongly releases Ca++ upon stimulation with CXCL12, showed no Ca++ release upon GPR15LG treatment." (PMID 40394646, 2025). "As determined using flow cytometry analysis, acute monocytic leukemia MOLM13 cells and acute lymphoblastic leukemia CEM cells overexpressed CXCR4 on their surface while human pancreatic adenocarcinoma cells were negative for human CXCR4." (PMID 35547755, 2022). "Furthermore, in vivo, continuous CXCR4 inhibition does not prevent acute lymphoblastic leukemia xenografts from developing CNS invasion." (PMID 37444576, 2023).
acute lymphoblastic leukemia (continued). "Similarly, Philadelphia chromosome-positive acute lymphoblastic leukemia (Ph+ALL), characterized by chromosomal translocations between chromosomes 9 and 22, resulting in the expression of an oncogenic BCR-ABL1 fusion protein, relies on CXCR4 for the survival of BCR-ABL1-transformed mouse preB cells." (PMID 40427609, 2025).
pancreatic ductal adenocarcinoma (36 papers, 2012 to 2026). An infiltrating adenocarcinoma that arises from the epithelial cells of the pancreas. "The CXCL12/CXCR4 axis may play an important role in the deproliferative response of pancreatic ductal adenocarcinoma, whereas loss of CXCR4 induces undifferentiated carcinomas with altered pancreatic phenotype without differentiated response." (PMID 34449964, 2021). "The inhibition of chemokine receptors (CXCR-4 inhibitor) in a pancreatic ductal adenocarcinoma revealed synergistic effect in combination with anti-PD-L1 treatment." (PMID 40860824, 2025). "The analysis of the data from the phase IIa study (NCT02826486) suggests that a combination of PD-1 blockade and CXCR4 antagonist can lead to an improvement in pancreatic ductal adenocarcinoma survival." (PMID 38791414, 2024). "In pancreatic ductal adenocarcinoma, CXCR4 blockers can reactivate CD8+ T cells in the TME, enhancing the benefits of PD-1 immunotherapy." (PMID 36308553, 2023). "In a model of pancreatic ductal adenocarcinoma (PDAC), inhibiting the CXCL-12/CXCR4 axis mediated by cancer-associated fibroblasts (CAFs) using the CXCR4 inhibitor AMD3100 resulted in enhanced accumulation of T cells and regression of cancer." (PMID 37511431, 2023). "For examples, DLEU1 accelerates the development of pancreatic ductal adenocarcinoma carcinogenesis through the miR-381/CXCR4 axis." (PMID 34113562, 2021). "Among the primary tumors for which we had a good number of cases, we found significant percentages of CXCR4+ cases for squamous cell carcinoma of the lung, clear cell renal cell and papillary carcinomas of the kidney, and ductal adenocarcinoma of the pancreas." (PMID 29088715, 2017). "Further supporting the investigation of chemokine inhibitors, recent findings from the COMBAT study highlight the effectiveness of the CXCR4 antagonist BL-8040 combined with pembrolizumab and chemotherapy in patients with pancreatic ductal adenocarcinoma (PDAC)." (PMID 40134607, 2025). "DLEU1 exacerbates pancreatic ductal adenocarcinoma through the miR-381/CXCR4 axis." (PMID 35619131, 2022). "Notably first clinical data shows CXCR4 inhibition in human pancreatic ductal adenocarcinoma also increased CD8+ T cell infiltration into the tumour." (PMID 35479076, 2022). "For example, overexpression of CXCR4 and SDF-1alpha, as validated targets of miR-1, were associated with local recurrence and distant metastasis in PCa and poor prognosis in stage II pancreatic ductal adenocarcinoma, respectively." (PMID 24967583, 2014). "In pancreatic ductal adenocarcinoma, combination therapy with anti-PD-L1 antibody and AMD3100, a selective CXCR4 antagonist, increases T cell accumulation in tumor tissue by suppressing CXCR4-mediated exclusion of cytotoxic T cells." (PMID 35884382, 2022). "Seo, Jiang showed that pancreatic ductal adenocarcinoma cell killing within the slice was mediated by CTL activity following 6-days of combined PD-1 and C-X-C chemokine receptor type 4 (CXCR4) blockade." (PMID 34988013, 2021). "In pancreatic ductal adenocarcinoma, FAP-positive CAFs suppressed the effects of anti-PD-L1 treatment through CXCL12/CXCR4 signalling." (PMID 31462002, 2019). "The aim of the present study was to investigate the association between the expression of chemokine receptors CCR7 and CXCR4 and vascular endothelial growth factor (VEGF)-C and the lymph node metastasis of pancreatic ductal adenocarcinoma (PDAC)." (PMID 23761820, 2013). "Within CSCs of pancreatic ductal adenocarcinoma, the combined expression of CD133 and CXCR4 correlated with an increased ability for invasion and metastatic spread that could be prevented by the blockage of CXCR4." (PMID 37108193, 2023).
pancreatic ductal adenocarcinoma (continued). "The prognostic role of CXCR4 was confirmed in a recent meta-analysis, including a total of 11 relevant articles involving 1439 pancreatic ductal adenocarcinoma (PDAC) patients, indicating CXCR4 as a negative prognostic marker associated with the risk of lymph node involvement and distant metastasis." (PMID 32260318, 2020). "Considering that ICCs contain a heterogeneous cell population, we used the pancreatic ductal carcinoma cell line, CFPAC-1, that expresses CXCR4 (data not shown) and shares adhesion and migration characteristics with those of ICCs." (PMID 22761699, 2012).